DACH1 (dachshund family transcription factor 1)
Diseases named in the same sentence as DACH1 in open-access papers (continued):
Sharing a sentence is not in itself a finding about the gene and the disease.
lung carcinoma (continued). "Stable overexpressing DACH1 in cultured lung cancer cells remarkably decreased CXCL1 protein." (PMID 31998654, 2019). "Suppression of DACH1 is also involved in breast and lung cancer." (PMID 31041889, 2019). "Therefore, we performed the correlation analysis between CXCL1 and DACH1 in lung cancer cell lines and cancer tissues." (PMID 31998654, 2019). "Previous finding demonstrated that tumor derived CXCL1 promoted the growth of lung cancer, our study suggested that the tumor suppress function of DACH1 might be through inhibiting CXCL1." (PMID 31998654, 2019). "Downregulation of DACH1 suggests unfavorable prognosis of lung cancers." (PMID 26810067, 2016). "Indeed, our in vitro experiment confirmed the growth inhibitory function of DACH1 when overexpressed in lung cancer cells." (PMID 26810067, 2016). "Decreased expression of DACH1 is involved in the initiation and development of lung cancer, which might be an adverse prognostic factor of lung adenocarcinoma." (PMID 26810067, 2016). "When compared to wild-type lung cancer cells, DACH1 overexpression in LTEP-α-2 and A549 cells blocks cell cycle progression and thus negatively influence tumor cell growth and invasion, while this alteration can be significantly prevented by the co-infection of PRX3." (PMID 26810067, 2016). "Thus, downregulation of DACH1 in lung cancer tissues might be an adverse prognostic factor, which should be extensively evaluated in further studies." (PMID 26810067, 2016). "However, the biological function of DACH1 in lung cancer is still not well understood." (PMID 26810067, 2016). "However, the mechanism by which DACH1 regulates lung cancer growth is not fully understood." (PMID 25788272, 2015). "We detected the expression of DACH1 in NSCLC cell lines, MRC5 cells and the KRAS-oncogene-driven lung cancer mice." (PMID 33435990, 2021). "We are inspired by these studies and conducted relevant mechanism explorations to prove the relationship between DACH1 and CXCL8 in lung cancer." (PMID 29636079, 2018). "Our study also determined that DACH1 significantly downregulates PRX3 gene expression, which is overexpressed in both of the two lung cancer cells employed in this study." (PMID 26810067, 2016). "There was an inverse correlation between DACH1 mRNA levels and CXCL5 in both lung cancer cell lines and human NSCLC tissues." (PMID 25788272, 2015). "To further explore the functional relationship between DACH1 and CXCL5, we searched lung cancer cell lines and tumor tissues database for mRNA expression." (PMID 25788272, 2015). "It suggested the specificity of correlation between DACH1 and CXCL8 in lung cancer." (PMID 29636079, 2018). "Moreover, as with prostate cancer, a reverse relationship between DACH1 and CXCL5 was reported in tumor samples and low DACH1 correlated with reduced survival in lung cancer patients." (PMID 26682253, 2015). "Importantly, there was an inverse relationship between the expression of DACH1 and CXCL5 in human lung cancer cell lines and NSCLC tissues." (PMID 25788272, 2015).
prostate carcinoma (17 papers, 2012 to 2025). A carcinoma that arises from epithelial cells of the prostate gland. "For example, the deletion of the DACH1 gene occurs in up to 18% of human prostate cancer cases, and its loss in mouse prostate cancer models has been shown to enhance prostatic intraepithelial neoplasia and DNA damage." (PMID 40370966, 2025). "A reduced abundance of DACH1 in human prostate cancer, associated with either gene deletion or promoter DNA methylation, correlated with poor outcomes." (PMID 37095257, 2023). "DACH1 is a transcriptional repressor and tumor suppressor gene frequently mutated in melanoma, bladder, and prostate cancer." (PMID 33378353, 2020). "DACH1 is a known tumor suppressor gene in breast, colon, and renal cancer and frequently mutated in melanoma, bladder, and prostate cancer." (PMID 33378353, 2020). "The loss of DACH1, which induces proliferation and invasion of tumor cells, has been observed in prostate cancer, endometrial cancer, renal cancer, and gastric cancer." (PMID 29636079, 2018). "DACH1 is expressed extensively in normal tissues and loss of DACH1 expression was reported related to poor prognosis in breast, endometrial and prostate cancers." (PMID 24912879, 2014). "In addition, DACH1 associates with the estrogen and androgen receptors (ER and AR) to regulate signal transduction and proliferation of breast and prostate cancer cells." (PMID 25788272, 2015). "In human prostate cancer, reduced DACH1 levels, often due to gene deletion or promoter DNA methylation, were correlated with poor clinical outcomes." (PMID 38956663, 2024). "DACH1 is located within the 13q21.31-q21.33 region, which is deleted in poor-prognosis prostate cancer." (PMID 37095257, 2023). "Immunostaining for DACH1 protein was conducted in tissue microarrays (TMAs) of 68 cases in triplicate 1 mm biopsy cores of primary prostate cancer with matched normal/benign tissue." (PMID 37095257, 2023). "In a subset of DACH1-deleted prostate cancers, we showed that DACH1 was co-deleted with RB (in 5 databases, co-homozygous-deletion of RB with DACH1 occurred in 15%, 5.3%, 0%, 1.4%, and 9%)." (PMID 37095257, 2023). "In the current studies, we identified homozygous deletions of DACH1 in between 3 and 18% of prostate cancers in six distinct cohorts." (PMID 37095257, 2023). "AR activity expressed as a z score for each prostate cancer subtype also showed an increase in the DACH1 deletion group as compared to normal samples." (PMID 37095257, 2023). "In prostate cancer, it has been demonstrated that DACH1 was negatively correlated with the expression of CXCL8 and able to antagonize the effects of CXCL8 on cellular migration." (PMID 29636079, 2018). "CXCL8 was identified as a downstream target of DACH1 in the process of suppression of cell proliferation and migration in breast and prostate cancer." (PMID 29636079, 2018). "DACH1 level is also found decreased in prostate cancer, and re-introduction of DACH1 inhibits prostate cancer cell proliferation in vitro." (PMID 26810067, 2016). "Reduced DACH1 expression also correlates with poor prognosis in prostate cancer and lung and hepatocellular carcinoma patients." (PMID 27203207, 2016). "Dach1 gene deletion in mice was shown to dramatically increase IL-8 and IL-6 abundance by nearly 1000-fold and thus promote prostate cancer cellular migration." (PMID 27203207, 2016). "DACH1 mRNA expression was reduced in metastatic human prostate cancer and DACH1 abundance was inversely correlated with IL-6 and IL-8." (PMID 26682253, 2015). "DS domain of DACH1 protein was required for inhibition of growth in breast and prostate cancer cells." (PMID 25788272, 2015). "Using prostate cancer cell lines of distinct genetic background, DACH1 was shown to inhibit proliferation in vitro and tumor growth in vivo of both AR negative cancer cell (PC-3) and castration resistant AR positive cell (C4-2 and 22RV-1)." (PMID 26682253, 2015).
prostate carcinoma (continued). "Furthermore, studies have shown that DACH1 expression is reduced, and that overexpression of DACH1 can inhibit the growth of prostate cancer cell lines." (PMID 38956663, 2024). "Given that DACH1 and RB1 deletion may co-occur in prostate cancer, we sought to determine the functional significance of DACH1 gene deletion, independently of RB1, in the onset and progression of PCa, using a murine model." (PMID 37095257, 2023). "The role of TGFβ hyperactivation in DACH1 deletion prostate cancer warrants further analysis." (PMID 37095257, 2023). "Combined with previous finding that DACH1 represses ligand induced transcriptional activation of the androgen receptor and prostate cancer cellular proliferation in tissue culture, it is likely that DACH1 conveys distinct functions at different stages of prostate cancer onset and progression." (PMID 26682253, 2015). "And other study showed that DACH1 repressed CXCL6 and CXCL8 in a dose-dependent manner, and repression required the DS domain in prostate cancer." (PMID 31998654, 2019). "Thus, deregulation of Dach1 alone, like deregulation of CHD, ERG1, or ETV1, is insufficient to drive prostate cancer in the mouse prostate." (PMID 37095257, 2023). "Furthermore, DACH1 binds Smad4 and NCoR to repress TGF-β signaling, enhances chemosensitivity by inducing the expression of P21, and regulates hormone levels in breast and prostate cancers." (PMID 30261897, 2018).
lung adenocarcinoma (15 papers, 2014 to 2025). A carcinoma that arises from the lung and is characterized by the presence of malignant glandular epithelial cells. "Loss of DACH1 causes tumor cells to proliferate and migrate, which has also been observed in prostate, kidney, and lung adenocarcinomas." (PMID 36959804, 2023). "To determine whether loss of DACH1 occurred in the early stage, we analyzed a gene expression dataset of 226 primary lung adenocarcinoma with pathological stage I-II, the result showed that expression of DACH1 mRNA was reduced in tumor tissues and inversely correlated with tumor stage." (PMID 25788272, 2015). "For the lung adenocarcinoma (LUAD) patients, the mutational rate in DACH1 was higher in the higher-score individuals, while CDKN2A and SMARCA4 were higher in the lower-score individuals." (PMID 41431699, 2025). "Among the factors that reduce CXCL1 expression and function in lung adenocarcinoma cells, dachshund family transcription factor 1 (DACH1) can also be mentioned." (PMID 38673949, 2024). "DACH1 expression exhibits cancer-type dependency wherein it was found to be downregulated in lung adenocarcinoma but upregulated in ovarian cancer." (PMID 32258117, 2020). "Further experimental results demonstrated the evidence that overexpression of DACH1 resulted in significant retardation of in vitro proliferation and invasion of lung adenocarcinoma cells." (PMID 26810067, 2016). "The colony formation assay revealed that the counts of colonies formed by DACH1-transfected lung adenocarcinoma cells were much less than those of WT cells." (PMID 26810067, 2016). "In this study, we explored the aberrant status, cancer-related functions, and potential tumor suppressing mechanisms of DACH1 in lung adenocarcinoma tissues and cell lines." (PMID 26810067, 2016). "In conclusion, DACH1 can inhibit the proliferation and invasion of lung adenocarcinoma through the downregulation of PRX3." (PMID 26810067, 2016). "In this study, we found the expression of Dachshund 1 (DACH1) is downregulated while peroxiredoxin 3 (PRX3) upregulated in both lung adenocarcinoma tissues and cells." (PMID 26810067, 2016). "In this study, we have identified reduced DACH1 expression in lung adenocarcinoma tissues and cells compared to normal tissues and cells, respectively." (PMID 26810067, 2016). "Transfection of DACH1 can significantly downregulate PRX3 expression in targeting lung adenocarcinoma cells." (PMID 26810067, 2016). "In order to evaluate the role of DACH1 in NSCLC, we established DACH1 expressing lung adenocarcinoma cell line A-427 and A549 by lentivirus transduction." (PMID 25788272, 2015). "While DACH1 usually functions as a tumour suppressor in renal cancer, lung adenocarcinoma, prostate cancer and breast cancer, inhibiting biological processes such as cell growth or promoting apoptosis, mainly through the inhibition of cell-cycle proteins, its role in CRC seems to be different." (PMID 40389405, 2025). "Another important gene identified in task 1, Dachshund 1 (DACH1) was found as an inhibitor that could prevent proliferation and invasion of lung adenocarcinoma cells as well as growth of tumor cells through repression of other factor genes." (PMID 31404060, 2019). "Besides, lower DACH1 expression significantly correlated with tumor diameter and tumor invasion in all the 36 patients diagnosed with lung adenocarcinoma in our hospital during the past months." (PMID 26810067, 2016). "Considering our experimental results and previous publications, it can be concluded that the inhibitory role of DACH1 in the proliferation and invasion of lung adenocarcinoma should be ascribed to the downregulation of its transcriptional target, Prx3, by competing with FOXM1 for promoter binding." (PMID 26810067, 2016).
lung adenocarcinoma (continued). "Besides, our study is the first study to statistically reveal that low expression of DACH1 significantly correlated with tumor diameter and invasion in 36 patients diagnosed with lung adenocarcinoma tumor." (PMID 26810067, 2016). "Therefore, combined detection of CXCL1 and DACH1 could more precisely predict prognosis of lung adenocarcinoma." (PMID 31998654, 2019). "Considering the downregulation of DACH1 and upregulation of PRX3 expression in human lung adenocarcinoma cells and tissues, we hypothesized that there may be a negative correlation between their intracellular levels." (PMID 26810067, 2016). "Moreover, we observed a negative correlation between DACH1 and PRX3 expression in clinical lung adenocarcinoma samples and cultured cancer cells." (PMID 26810067, 2016).
colorectal cancer (14 papers, 2014 to 2025). A primary or metastatic malignant neoplasm that affects the colon or rectum. "However, it does not appear to be indispensable for cancer-cell proliferation and cancer progression since some of the colorectal cancers we examined were characterized by complete or partial loss of DACH1 protein expression." (PMID 24472434, 2014). "Since the cyclin D1 is one of the major downstream targets of Wnt/β-catenin signaling and the DACH1 is associated with Wnt pathways in colorectal cancer, we hypothesized that DACH1 could also repress cyclin D1 abundance via inactivation of Wnt signaling in HCC." (PMID 25940701, 2015). "The relationship between DACH1 methylation and transcriptional silencing in colorectal cancer tissues was investigated using methylation data from TCGA (n = 589)." (PMID 40370966, 2025). "The present study revealed a crucial epigenetic mechanism in colorectal cancer (CRC) progression involving the aberrant regulation of DACH1 by DNMT1 based on the combination of clinical sample analysis with bioinformatic databases." (PMID 40370966, 2025). "Previous studies have demonstrated that miR-552 functions as a potential oncogene in a series of cancer types and figure out several downstream targets, such as AJAP1 in liver cancer, Smad2 and DACH1 in colorectal cancer, TIMP2 and WIF1 in osteosarcoma 28-32." (PMID 33867818, 2021). "Previous studies showed that miR-552 promotes colorectal cancer cells proliferation and migration by directly targeting DACH1 via the Wnt/β-catenin signaling pathway." (PMID 31815639, 2019). "Previous studies showed that miR-552 is upregulated in colorectal cancer tissues and promotes colorectal cancer cells progression by directly targeting DACH1." (PMID 31815639, 2019). "In vitro studies have shown that DACH1 negatively regulates colorectal cancer via Wnt pathway and malignant peripheral nerve sheath tumors through RAS signaling." (PMID 30261897, 2018). "DACH1 was found frequently methylated in hepatocellular carcinoma and colorectal cancer in our previous study." (PMID 24912879, 2014). "For instance, miRNA-552 promotes colorectal cancer progression via targeting DACH1." (PMID 35465017, 2022). "Besides, Wnt-signaling pathway is reported to mediate the oncogenic role of miR-552 by Dachshund family transcription factor 1 in colorectal cancer." (PMID 33869776, 2021). "As a potential tumor suppressor, DACH1 promoted hypermethylation and correspondingly reduced expression of DACH1 was observed in several kinds of cancers, including esophageal cancer, gastric cancer, colorectal cancer and hepatocellular carcinoma." (PMID 25322986, 2014). "TGF-β signalling was inhibited by DACH1 in breast and colorectal cancer by DS domain." (PMID 24912879, 2014). "DACH1 is frequently methylated in hepatic and colorectal cancer." (PMID 24912879, 2014). "DACH1 has been shown to inhibit TGF-β signalling in breast and colorectal cancer." (PMID 24912879, 2014).
endometrial cancer (10 papers, 2012 to 2025). Primary or metastatic malignant neoplasm involving the endometrium (mucous membrane that lines the endometrial cavity). "In this study, we utilized the Oncology Research Information Exchange Network (ORIEN) Avatar database to determine the frequency of DACH1 mutations in patients with endometrial cancer in our Kentucky population." (PMID 33378353, 2020). "Kentucky women with endometrial cancer had an increased frequency of DACH1 mutations (12/65 patients, 18.5%) compared to The Cancer Genome Atlas (TCGA) endometrial cancer population (25/586 patients, 3.8%) with p-value = 1.04E-05." (PMID 33378353, 2020). "Further evidence of its TSG function is provided by the observation that DACH1 homozygous deletion stimulates tumorigenesis in glioma cells, and loss of DACH1 occurs in high FIGO surgical stage endometrial cancers." (PMID 24392136, 2014). "DACH1 could provide a novel therapeutic target for immunotherapy in this ultrasensitive group of endometrial cancers with increased tumor mutation burden." (PMID 33378353, 2020). "DACH1 mutations are prevalent in Kentucky patients with endometrial cancer." (PMID 33378353, 2020). "We first compared tumor mutation counts in the TCGA PCA endometrial cancer and carcinosarcoma cohorts between DACH1 mutated patients and wild-type and found clinically significant differences with a median of 8972 in DACH1 mutants vs. 65 in DACH1 wild-type (p-value = 7.35e-09)." (PMID 33378353, 2020). "Finally, the majority of literature related to DACH1 in endometrial cancer is at the protein expression level, and the relationship to DACH1 mutation and protein expression is currently unknown." (PMID 33378353, 2020). "While less studied in uterine cancer, nearly all normal endometrial samples show nuclear expression of DACH1, with DACH1 expression lost in more than half of endometrial cancers." (PMID 33378353, 2020). "Still, whereas a number of studies have demonstrated that DACH1 profoundly improves the prognosis of cancer patients as a tumor suppressor, a few studies have also observed an oncogenic role of DACH1 in endometrial cancer and mixed lineage leukemia (MLL)." (PMID 27203207, 2016). "DACH1 is a tumor suppressor gene, whose expression is reduced in prostate and endometrial cancer correlating with increased tumor progression and invasion." (PMID 23565812, 2013). "Loss of DACH1 expression is associated with poor prognostic factors, including higher FIGO surgical stage, positive peritoneal cytology, and lymph node positivity in endometrial cancer." (PMID 33378353, 2020).